FMR1 (fragile X messenger ribonucleoprotein 1)
Diseases named in the same sentence as FMR1 in open-access papers (continued):
Sharing a sentence is not in itself a finding about the gene and the disease.
fragile X syndrome (continued). "Interestingly, PVNH has also been reported in patients with Fragile X syndrome due to marked expansion and instability of the CGG trinucleotide repeat within the FMR1 gene." (PMID 29738522, 2018). "Fragile X syndrome (FXS) is a neurodevelopmental disorder resulting from silencing of the fragile X mental retardation gene (FMR1) on the X chromosome, leading to reduced production of Fragile X Mental Retardation Protein (FMRP) that causes atypical brain development and function." (PMID 28316753, 2017). "Here, we report a weak transcriptional activity of the FMR1 gene and the absence of FMRP protein after Fragile X syndrome cell lines treatment with two FDA approved inhibitors of histone deacetylases, romidepsin and vorinostat." (PMID 29209628, 2017). "The 5′ untranslated region of the FMR1 gene contains a CGG repeat that varies in length, causing Fragile X syndrome at over 200 repeats, with methylation and silencing of the FMR1 gene and lack of FMRP expression." (PMID 27614355, 2016). "Expansions exceeding 200 CGG repeats are associated with hypermethylation of the promoter region, transcriptional silencing of the gene, and reduction or absence of expression of the FMR1 protein (FMRP), which result in fragile X syndrome (FXS)." (PMID 27980694, 2016). "For psychiatric disorders involving a cerebellar pathology, there are more specific models, such as Fmr1 gene knockout mice for fragile X syndrome or neuroligin-3 knockout mice, a model for nonsyndromic autism." (PMID 26331028, 2014). "The discovery of the FMR1 gene defects over twenty-two years ago has led to significant advances in understanding the critical role of FMRP in synaptic plasticity and the molecular events of the fragile X mental retardation syndrome." (PMID 24658146, 2014). "Lack of the fragile X mental retardation protein leads to Fragile X syndrome (FXS) while increased levels of FMR1 mRNA, as those observed in premutation carriers can lead to Fragile X- associated tremor ataxia syndrome (FXTAS)." (PMID 23692864, 2013). "Unless FMR1 reactivation is more effective in vivo our results indicate that methotrexate has no role in the treatment of fragile X syndrome." (PMID 24020679, 2013). "As the world of RNA-binding proteins is expanding, understanding the role of Caprin1 and of other RNA-binding FMRP interactors, will be essential to unravel the functions altered by lack of FMR1 expression in the fragile X syndrome." (PMID 22737234, 2012). "Fragile X syndrome (FXS) is the most common inherited form mental impairment that is caused by an expanded CGG trinucleotide repeat in the 5′ untranslated region of the fragile X mental retardation (FMR1) gene leading to gene silencing and loss of the fragile X mental retardation protein (FMRP)." (PMID 22888453, 2012). "Despite the hemizygosity of FMR1 gene, the patient does not present Fragile X syndrome features, since the normal X-chromosome is not subject to methylation." (PMID 20646274, 2010). "In patients with Fragile X syndrome, a CGG trinucleotide repeat located in the 5′-UTR of the fragile X messenger ribonucleoprotein 1 (Fmr1) gene expands from ~50 to >200, resulting in hypermethylation of the promoter region and epigenetic silencing of the Fmr1 gene." (PMID 40931164, 2026). "The study’s aim was to evaluate electroretinographic (ERG) alterations in Fragile X syndrome (FXS), FMR1 premutation carriers, and controls, and to explore correlations with peripheral blood FMRP expression levels and behavioral outcomes." (PMID 40725073, 2025). "Fragile X syndrome (FXS) occurs when there are more than 200 CGG repeats, leading to the silencing of the FMR1 gene, with deficits in the FMRP." (PMID 40076819, 2025).
fragile X syndrome (continued). "Electrophysiology studies on Fmr1 KO mice hippocampi first identified a peculiar alteration of synaptic plasticity: in particular, long-term depression induced by metabotropic glutamate receptors (mGluR-LTD) was abnormally enhanced, leading to the “mGluR theory” of Fragile X Syndrome." (PMID 40141138, 2025). "Here, we quantified FMR1 somatic variation in post-mortem brain tissue from individuals with FXTAS (n = 6) and Fragile X syndrome (FXS, n = 2) by applying amplification-free, targeted, long-read sequencing." (PMID 41278766, 2025). "In the Fmr1 model of ASD, which recapitulates fragile X syndrome (FXS), a failure of diacylglycerol Lipase α (DAGL-α), the main enzyme responsible for synthesizing 2-AG, was associated with metabotropic glutamate 5 receptor (mGlu5R) deficits." (PMID 40605060, 2025). "Fragile X Syndrome (FXS), the leading known inherited cause of atypical behaviors associated with autism spectrum disorders (ASD), arises due to the reduced expression or absence of the Fragile X Messenger Ribonucleoprotein 1 (FMRP)." (PMID 41469555, 2025). "Expansion of CGG repeats in the 5′ UTR of FMR1 results in abnormal DNA methylation and FMRP protein silencing, leading to fragile X syndrome (FXS)." (PMID 38242131, 2024). "Seventy patients underwent extra FMR1 testing in addition to CTPS, who had prominent clinical features especially the facial characteristics such as long face, prominent ears, and prominent jaw, and 4 out of 70 (5.71%) obtained positive results and were lately diagnosed with Fragile X syndrome." (PMID 35741772, 2022). "Furthermore, the ACMG, NZ, and NY recommend FMR1 testing for all boys without an etiology for ASD that systematically excluded fragile X syndrome." (PMID 36553329, 2022). "Testing for the Fragile X syndrome (OMIM 300624) did not identify FMR1 expansion." (PMID 33603162, 2021). "For instance, FMR1, a FRAXA-residing gene which harbors trinucleotide repeat expansions in Fragile X syndrome (FXS) patients, correlates with aggressiveness and lung metastasis probability in triple-negative breast cancer." (PMID 32260317, 2020). "Both FMR4 and FMR6 are thought to regulate FMR1 stability, splicing, subcellular localization and translational efficiency in FXTAS, and have been proposed to be useful biomarkers allowing for early detection and therapeutic intervention in fragile X syndrome and FXTAS." (PMID 32777047, 2020). "Interestingly, a recent study in a rat model of fragile X syndrome demonstrated that adult Fmr1 animals no longer exhibited cognitive deficits following brief lovastatin treatment at young age only." (PMID 32071072, 2020). "Similarly, previous studies have found that Fragile X Syndrome, another kind of ID, is caused by the absence of the Fragile X Mental Retardation Protein (FMRP), due to mutations of the FMR1 gene." (PMID 32858868, 2020). "Thus, studies on the hippocampus of the Fmr1-null mice, the most common murine model of Fragile X syndrome, did not provide clear information relative to the number, density, and maturity of the dendritic spines." (PMID 33328904, 2020). "For example, fragile X syndrome (FXS) has been attributed to the absence of fragile X mental retardation 1 (FMR1) gene expression due to a long CGG tri-nucleotide repeat in the FMR1 gene 5′-UTR adjacent to the promoter that results in the FMR1 gene’s epigenetic silencing." (PMID 31921300, 2019). "In addition, the ideal control tissue for these studies would have been brain samples from a fully methylated Fragile X Syndrome patient, as such a patient would presumably produce no FMR1 or ASFMR1 mRNA." (PMID 31665086, 2019). "Even though it was proposed that these paralogs could partially compensate for the loss of FMRP, it was later shown that the expression of both FXR1P and FXR2P is not altered in patients with fragile X syndrome or in Fmr1 knockout mice." (PMID 31112584, 2019).
fragile X syndrome (continued). "While fragile-X syndrome has a specific and detectable molecular phenotype (lack of FMR1 protein), the limitation of most animal studies is that many human psychiatric diseases are defined by behavioural traits that can only be partially observed in other species." (PMID 30832291, 2019). "Importantly, these effects could be achieved in adult Fmr1 knockout mice with a single administration of FRAX486, demonstrating the potential for therapy in adults with fragile X syndrome." (PMID 25767435, 2015). "Fragile X syndrome (FXS) is caused by an expanded CGG repeat (> 200 repeats) in the 5' untranslated portion of the fragile mental retardation 1 gene (FMR1), leading to deficiency or absence of the FMR1 protein (FMRP)." (PMID 20858229, 2010). "The FMR1 gene (MIM 309550), located on the X-chromosome, is one of the most extensively studied genes in relation to ASD, primarily due to its role in Fragile X Syndrome (FXS) (MIM 300624)." (PMID 39769462, 2024). "More than 95% of fragile X syndrome is caused by reduced or absent fragile X intellectual disability protein 1 (FMRP) synthesis due to dynamic mutation expansion of the CGG triplet repeat in the 5'UTR and abnormal methylation of the FMR1 (fragile X messenger ribonucleoprotein 1) gene [OMIM 309550]." (PMID 37745859, 2023). "Fragile X syndrome (FXS), the most common form of heritable intellectual disability, is caused by a disruption of the fragile X mental retardation 1 gene (FMR1; also called fragile X messenger ribonucleoprotein 1 gene) on the X chromosome and the resultant absence of FMR protein (FMRP)." (PMID 35626665, 2022). "For fragile X syndrome (FXS), an inherited intellectual disability in males, FMR1 was reactivated after the heterochromatin status switched, by targeting demethylation of the CGG expansion using dCas9-Tet1/single guide RNA (sgRNA) in FXS iPSCs." (PMID 34887928, 2021). "Although ERK signaling in Fmr1 mice is not increased under baseline conditions, it has been shown that the ERK pathway in these mice is hypersensitive and contributes to the excessive protein synthesis which is considered one of the core mechanisms underlying fragile X syndrome pathophysiology." (PMID 32071072, 2020). "The absence of the FMR1-encoded protein, fragile X mental retardation protein (FMRP), will cause clinical features of fragile X syndrome (FXS), including ASD behaviors." (PMID 32824515, 2020). "Finally, family history of mental retardation suggestive of fragile X syndrome, which could be a clue for presence of FMR1 premutation in the proband, was not investigated." (PMID 31158927, 2019). "A hyperactivated mTORC1–eIF4E pathway is linked to impaired synaptic plasticity in fragile X syndrome, an autistic disorder caused by lack of fragile X mental retardation protein (FMRP) due to mutation of the FMR1 gene, suggesting that downstream mTOR signaling might be causally linked to ASDs." (PMID 23533374, 2013). "Previous studies have shown that trace fear memory is impaired in Fmr1 KO mice, accompanied by alterations in synaptic plasticity in ACC, suggesting that the dysfunction of ACC due to lack of FMRP may be responsible for certain types of mental disorders in fragile X syndrome." (PMID 22867433, 2012). "In contrast, when the number of CGGs exceeds 200 repeats (full mutation) the FMR1 gene is silenced resulting in the absence of FMRP and the clinical manifestations of fragile X syndrome (FXS, OMIM#300624; ORPHA:908): intellectual disability and characteristic dysmorphic features." (PMID 35456280, 2022). "Despite the relatively high CGG expansions, the expression of the FMR1 gene product FMRP, was still detectable at PND9, PND21, and PND210 in hippocampus, cerebellum, and cortex and not absent as observed in models of Fragile X syndrome." (PMID 27147951, 2016). "In fragile X syndrome, CGG repeat lengths exceed 200, resulting in silencing of FMR1 and absence of its protein product, fragile X mental retardation protein (FMRP)." (PMID 25290064, 2014).
fragile X syndrome (continued). "Fragile X syndrome (FXS), the leading cause of inherited mental retardation, is due to expansion and methylation of a CGG sequence in the FMR1 gene, which result in its silencing and consequent absence of FMRP protein." (PMID 22397687, 2012). "In addition to histone hyperacetylation, DNA demethylation of specific genes is also triggered by VPA in HEK293 cells, but not in FXS (fragile X syndrome) lymphoblastoid cell lines in which the FMR1 gene is silenced by DNA methylation or in mouse embryos." (PMID 22206001, 2011). "However, neither adult fragile X patients nor adult Fmr1 KO mice show any differences in the number of neurons and glia compared with controls, raising questions about the potential significance of increased early neurogenesis to the pathogenesis of fragile X syndrome." (PMID 20386739, 2010). "In Fragile X syndrome, expansion of the CGG trinucleotide in the FMR1 gene to more than 200 repeats leads to reduced or absent production of the FMRP protein, which plays a key role in regulating the translation of proteins involved in dendritic development and synaptogenesis." (PMID 41465426, 2025). "The cause of fragile X syndrome (FXS) is the expansion of CGG repeats in the 5′UTR of the FMR1 gene and subsequent hypermethylation at the CpG island in the promoter region of this gene, leading to transcriptional silence of the mRNA and absence of FMRP translation." (PMID 27042357, 2016). "Individuals with an allele within the normal range (5–44 CGG repeats) are considered unaffected, while full mutation alleles (>200 CGG repeats) result in transcriptional silencing of the FMR1 gene, absence of fragile X mental retardation 1 protein (FMRP) and fragile X syndrome." (PMID 21818263, 2011). "The Fragile X Messenger Ribonucleoprotein 1 (FMRP), absent or dysfunctional in the Fragile X Syndrome (FXS), it is an RNA binding protein whose activity is essential for brain functions." (PMID 37379311, 2023).
Intellectual disability (263 papers, 2008 to 2026). "The loss of Fmr1 protein modulates many cell biological processes and leads to the emergence of intellectual disability and autism." (PMID 42041789, 2026). "Case 21 had a deletion segment including the Xq27.3-q28 duplication syndrome region, with FMR1 being an important pathogenic gene in this region, expressed more in the brain, and being an important gene causing intellectual disabilities." (PMID 40224383, 2025). "In a study for the prevalence of FMR1 mutations in 508 males with normal CGG repeat expansions, who had clinical signs of developmental delay and intellectual disability, two novel missense mutations in FMR1 were reported." (PMID 39839505, 2025). "It has been suggested that mutations in FMR1 are associated with diverse mental disorders, including intellectual disability, autistic abnormality, and schizophrenia." (PMID 39604386, 2024). "Because FXS is associated with intellectual disability, we next investigated the effects of mGluR7 activation on learning and memory in Fmr1 KO mice." (PMID 38374465, 2024). "Studies in past years suggest that mutations in the fragile X mental retardation 1 (FMR1) are associated with diverse mental disorders including intellectual disability, autistic spectrum disorder, and schizophrenia." (PMID 39604386, 2024). "Genetic variants of DCX, COMT and FMR1 have been linked to neurodevelopmental disorders related to intellectual disability and social behavior." (PMID 35590332, 2022). "FXS is a leading inherited cause of ASD and intellectual disability, resulting from a mutation in the FMR1 gene and loss of its protein product FMRP." (PMID 36077195, 2022). "Fragile X syndrome (FXS, OMIM 309550) is the most common cause of inherited mental retardation that results from the expansion of CGG repeats in the 5’ untranslated region (5’ UTR) of the fragile X mental retardation 1 (FMR1) gene." (PMID 35222660, 2022). "An intriguing example is fragile X syndrome, a common form of inherited mental retardation which is caused by loss-of-function mutations in the fragile X mental retardation 1 (FMR1) gene." (PMID 35777956, 2022). "In samples of persons with intellectual disability, the contribution of FMR1 full mutations has been estimated to be 1–6%33,34." (PMID 35719251, 2022). "The most common monogenic cause of ASD is FXS, a neurodevelopmental disorder which causes intellectual disability attributed to FMRP protein deficiency as a result of a mutation in the FMR1 gene." (PMID 34276318, 2021). "Fragile X syndrome (FXS) is the most common inherited form of intellectual disability caused by a CGG repeat expansion in the 5′ untranslated region of the FMR1 gene." (PMID 32281281, 2020). "This locus encompasses a well-studied VNTR in the 5′-untranslated region of the FMR1 gene, which, when expanded, is the most common cause of mental retardation in males." (PMID 33139705, 2020). "Fragile X Syndrome (FXS) is the leading single-gene cause of Autism Spectrum Disorder (ASD) and intellectual disability (ID) caused by a CGG trinucleotide expansion in the FMR1 (Fragile X mental retardation 1) gene." (PMID 32531912, 2020). "Fragile X syndrome (FXS) is the most common inherited form of intellectual disability, resulted from the silencing of the Fmr1 gene and the subsequent loss of fragile X mental retardation protein (FMRP)." (PMID 31882402, 2020). "The first-ranked gene FMR1 was proved to be associated with mental diseases like mental retardation and autism, and five other genes (APP, SNCA, MAPT, SIRT2, APOE) are known to be associated to Alzheimer's disease." (PMID 32038710, 2019). "Fragile X syndrome is a form of human intellectual disability caused by a loss-of-function mutation of the fragile X mental retardation 1 (FMR1) gene." (PMID 31413047, 2019). "For instance, RNA binding protein FMRP encoded by fragile X mental retardation (Fmr1) gene plays an essential role in preserving ovarian function in mice and humans." (PMID 29955025, 2018).